MMP2 (matrix metallopeptidase 2)
Diseases named in the same sentence as MMP2 in open-access papers (continued):
Sharing a sentence is not in itself a finding about the gene and the disease.
tumor (continued). "Similar results were obtained by analyzing the association between the expression of the studied genes in tumor samples and patient survival (TIMP1, p = 0.5972; MMP2, p = 0.9627; MMP9, p = 0.8563)." (PMID 37509417, 2023). "In this experimental model, treatment with either anti-PD-1 antibody or MMP2 inhibitor alone significantly reduced tumor growth, while a combination treatment of MMP2 inhibitor and anti-PD-1 antibody achieved the best efficacy." (PMID 36788565, 2023). "MMPs exert important effects in tumor invasion and metastasis, among which MMP2, MMP3 and MMP9 are the main members that play crucial roles in the invasion and metastasis of cancer cells." (PMID 37100464, 2023). "Lactate induces the expression of TGF-β2 in gastric and lung cancers which upregulates the expression and activation of MMP-2, thereby promoting tumour cell metastasis." (PMID 36909729, 2023). "In NHPVA ADC, we discovered remarkable involvement of MMP2 in tumor angiogenesis, and the SEMA5A–PLXNB3 interaction was possibly related to neural invasion." (PMID 36725337, 2023). "In line with the high expression of TRIM9, the protein level of CEACAM6, Smad2/3 and MMP2 were upregulated in TRIM9 overexpressed tumor tissues." (PMID 37249822, 2023). "Invasive tumor cells are known to have a strong ability to degrade extracellular matrix through the activation of MMP2." (PMID 37990331, 2023). "After being taken up by tumor cells, the shield CPPs attached on the nanosystem were removed by overexpressed MMP-2 in tumor cells, and the ALA molecules were liberated through cleavage the hydrazine bonds at an acidic environment in tumor cells." (PMID 36923350, 2023). "Fc fragments of NISA can be exposed through hydrolysis of long-chain PEG5000 by highly expressed MMP-2 in tumor microenvironment." (PMID 35093074, 2022). "Under pathological conditions, activated MMP-2 can degrade the extracellular matrix components and break through the matrix barrier, leading to tumor invasion and metastasis." (PMID 35602129, 2022). "In the context of ESCC, a high positive rate of MMP-2 has been detected in relation to tumor differentiation degree, invasion depth and LNM so that occurrence of distant metastasis is facilitated." (PMID 35578338, 2022). "The results showed that tumor-derived DNA-treated SK-Hep1 cells exhibited significantly higher P-ErK1/2 and MMP2/9 activity, while sinobine hydrochloride reduced this increase." (PMID 35860597, 2022). "These vesicles are stable in blood circulation until they arrive at the tumor site, where matrix metalloproteinase-2 (MMP-2) cleaves their PEG corona and the acidic TME triggers the surface charge reversal of these vesicles." (PMID 35335881, 2022). "The VM contributes to tumor proliferation and invasion in many types of cancers through the upregulation of several proteins, including matrix metalloproteinase (MMP)-2, MMP-9, vascular endothelial growth factor (VEGF), and growth factor-β1 (TGF-β1)." (PMID 35747793, 2022). "We demonstrated that HOXD11 is a novel therapeutic target mediated by miR-138-5p promoting tumor metastasis of PSCC via the FN1/MMP2/MMP9 molecular pathway." (PMID 36151071, 2022). "Authors reported that the significantly decreased APRIL and increased BAFF, IL-8, and MMP2 expression was tumor-specific and deserves consideration in the development of new treatments." (PMID 35565369, 2022). "Subsequently, we detected MMP-2 and MMP-9 protein expression associated with tumor metastatic ability to explore possible mechanisms." (PMID 35936728, 2022). "In the tumor tissues, MMP2, which overexpressed vascular endothelia and stroma of tumor, cleaved lipid–peptide shell to release R300 and Dox." (PMID 35246962, 2022). "MMP-2, a protease involved in the degradation of tumor ECM, is relatively overexpressed in almost all tumors." (PMID 34466734, 2022). "FTS/YM155 NCs were cleaved in the tumor sites by secreted MMP‐2 to release TmSm and actively targeted cancer cells via TfR1 binding." (PMID 35600646, 2022).
tumor (continued). "Oral administration of luteolin appreciably declined the concentrations of tumor markers as well as expressions of MMP-2 and -9." (PMID 36247004, 2022). "Meanwhile, tumor cells can also stimulate the body to produce a large amount of MMP-2, which plays an important role in their own growth and migration." (PMID 35935313, 2022). "In the early stage of our study, we used RGD and ACPP to carry the anti-p21Ras scFv to integrin-expressing tumor cells and MMP2-expressing tumor cells, respectively." (PMID 35648774, 2022). "By contrast, the circBRWD3 knockdown tumor model exhibited opposite phenotypes with a decreased level of E-cadherin and increased levels of N-cadherin, Vimentin, MMP2, and MMP9." (PMID 36443711, 2022). "The inhibition of the matrix metalloproteinases MMP2 and MMP2 activation, which play an essential role in tumor metastasis, has been demonstrated before." (PMID 35646663, 2022). "In this study, TmSm was fused to the C‐terminus of the FTH1 gene via an MMP‐2‐sensitive peptide (P‐L‐G‐L‐A‐G), which is responsive to the tumor microenvironment for site‐specific release of the TmSm protein." (PMID 35600646, 2022). "Ki67 (the typical proliferation marker), TGF-β1 (the TGF-β/Smad pathway-related factor), and MMP2 (metastasis-related factor) protein expressions in tumor tissues were also decreased by ITGBL1 knockdown." (PMID 35584452, 2022). "Song and colleagues showed that Hsp90α, but not Hsp90β, stabilized MMP2 and protected it from degradation in tumour cells in an ATP-independent manner and was mediated by the middle domain of Hsp90α binding to the C-terminal hemopexin domain of MMP2." (PMID 35883467, 2022). "The objective of our study was to examine the expression of tumor-progression-associated MMPs (MMP-1, MMP-2, and MMP-9) and tissue inhibitors of metalloproteinases (TIMP-1 and TIMP-2) in locally invasive PTC and their relation to clinicopathological features." (PMID 36551933, 2022). "In cancer, higher MMP-2 and MMP-9 activities have been linked to not only tumor cell invasion but also angiogenesis." (PMID 35625802, 2022). "The reversion-inducing cysteine-rich protein with kazal motifs (RECK), initially considered a tumor suppressor gene, has been demonstrated to inhibit tumor invasion and metastasis by negatively regulating MMP2 and MMP9." (PMID 35562926, 2022). "Among the MMPs, matrix metalloproteinase -2 (MMP-2) activation is related to tumor progression and invasion." (PMID 35163164, 2022). "MMP2, also called gelatinase A, is strongly correlated with cancer progression, as it is rapidly produced by growing tumour cells." (PMID 36077415, 2022). "Further, their data revealed the modulation of tumor invasion and metastasis markers, such as MMP-2 and MMP-9, as well as FAK gene expression in CNE1 cells." (PMID 36015440, 2022). "These advanced nanoplatforms were able to efficiently undergo enzymatic hydrolysis in overexpressed MMP-2 environments to improve tumor treatment by the release of their cargoes." (PMID 36096856, 2022). "Many different enzymes have been found to be highly expressed in cancer cells and tumor tissues, including matrix metalloproteinase 2 (MMP-2), Cathepsin B, and hyaluronidase (HAase)." (PMID 35631699, 2022). "At acidic tumor site, the masking peptides became charge-neutral and separated from the nanoparticle surface by the cleavage of MMP-2." (PMID 34466734, 2022). "After accumulation at tumor sites, these nanoparticles were cleaved by matrix metallopeptidase 2 (MMP-2) enzyme, releasing Ato and ICG." (PMID 36145513, 2022). "Tipifarnib is a farnesyltransferase inhibitor with the potential of increasing radiosensitivity by blocking activity of the RAS- and RhoB-oncogen pathways while also reducing tumor hypoxia by controlling MMP2 expression." (PMID 35503461, 2022). "NCTD can inhibit the tumor vasculogenic mimicry via suppressing MMP-2 expression and blocking the Ephrin Type a Receptor 2/Focal Adhesion Kinase/Paxillin pathway." (PMID 36463199, 2022).
tumor (continued). "Those outcomes reveal that sinobine hydrochloride reverses the role of tumor-derived DNA in HCC cells via stimulating the ERK1/2/MMP2/9 signal path regulated by the CCL21-CCR7 axis." (PMID 35860597, 2022). "The increased calcium influx mediated by this repression impedes the localization of MT1-MMP and subsequent activation of MMP-2, preventing tumor cell metastasis." (PMID 36289525, 2022). "MMP-2 and ecto-5′-nucleotidase activity can degrade collagens as structural component of basement membranes and thus alter tumor microenvironment leading to increasing tumor heterogeneity." (PMID 36117723, 2022). "The mechanism of MMP-2 in AML patients is that it can hydrolyze the stromal membrane of tumor cells, enhance the adhesion between cells, and provide important conditions for the proliferation of tumor cells." (PMID 35935313, 2022). "We assessed the relationship between the expression level of POSTN and MMP-2 in NSCLC and found a positive significant correlation of POSTN expression level with MMP-2 in tumor cells (r = 0.5262, *** p < 0.001)." (PMID 35163164, 2022). "IL8 produced by tumour cells has been reported to stimulate both tumour and stromal cells to release angiogenesis‐related factors, such as MMP2/9, thus promoting tumour growth." (PMID 35224833, 2022). "MMP-9 expression is required for the angiogenic switch, whereas MMP-2 activates endothelial cell survival and proliferation and initiates integrin signaling to support the angiogenesis thereby contributing to tumor growth." (PMID 36250005, 2022). "Our mechanism studies showed us that proteins facilitating tumor metastasis, including MMP‐2 and MMP‐9, were downregulated by mMNS@Cal." (PMID 35111955, 2022). "In cancer, MMP9 and MMP2 appear to play a role in tumor invasion and angiogenesis and to mediate the tumor microenvironment." (PMID 34980260, 2022). "The αvβ integrin/ERK signaling pathway is one of the mechanisms by which MMP-2 expression is upregulated in tumor cells." (PMID 35163164, 2022). "Matrix metalloproteinases MMP2 and MMP9 are implicated in tumor angiogenesis and invasion, and these processes are regulated by some genes." (PMID 35912155, 2022). "In gastric cancer, Efp was found to cause poly-ubiquitination of specific protein 1 (SP1), a transcription factor that induces transcription of proteins including matrix metalloproteinases 2 (MMP2) and is involved in tumor growth, metastasis, and angiogenesis." (PMID 35954308, 2022). "Thrombospondin (TSP) 1 and platelet-derived PDGF promote tumor invasion and metastasis by upregulating MMP2/MMP9 expression and inducing EMT through the p38 MAPK signaling pathway." (PMID 35936717, 2022). "Collectively, we concluded that the basement membrane was disassembled or lost in the mxc tumor LG consistent with the higher expression of Mmp2." (PMID 36226812, 2022). "MMP-2 appeared over-expressed in 8 out of 9 tumor samples (89 %), with particularly high levels in sample T3, when compared to normal skin samples, where its expression was very low." (PMID 36518899, 2022). "In vivo, DCH inhibited tumour growth in mice, downregulated the expression of MMP2 and MMP9, and partially reversed EMT." (PMID 36408277, 2022). "The predicted expression considering the network in MMP-2-related pathways increased with tumor category." (PMID 35561164, 2022). "For example, the presence of bax, cleaved caspase-3, MMP2 and other substances was the material basis for circ_LARP4 to promote tumor growth and lung metastasis by upregulating parental gene expression." (PMID 36091137, 2022). "The tumor cells secrete matrix metalloproteases (MMPs), like MMP2 and MMP9, which helps to degrade the collagen matrix to make a path for invading cells." (PMID 35686673, 2022). "TIMP-2 regulates MMP-9 and MMP2 expression at the protein and mRNA levels and prevents further metastasis of tumor cells." (PMID 35770085, 2022).
tumor (continued). "Increased expression of MMP-2 was described to be correlated with intravasation and lymph node metastasis of tumor cells into the blood vessels." (PMID 35205628, 2022). "Tumour cells and fibroblasts communicate with each other, including autocrine and paracrine factors, including IL-8, resulting in the upregulation of MMP2 and MMP9 degradable extracellular matrix (ECM) components that trigger tumour invasion." (PMID 35941973, 2022). "Further, the authors revealed that miR-145-5-p controlled tumor cell migration and invasion by suppressing the expression of Matrix Metallopeptidase 2 (MMP2), N-cadherin, Focal adhesion kinase and Matrix Metallopeptidase 7 (MMP7)." (PMID 35269744, 2022). "MMP2/9 activation subsequently increases the invasion of the host stroma by tumour cells, ultimately contributing to tumour angiogenesis and metastasis." (PMID 35224833, 2022). "Extracellular matrix degradation through MMP-2, a fundamental step in the acquisition of metastatic properties of tumor cells, takes part in the wider and more complex process of EMT." (PMID 36230799, 2022). "MT1-MMP, a multifunctional enzyme, is also involved in the activation of pro-MMP-2, leading to tumor growth." (PMID 36250005, 2022). "CXCR4-oe and CCR7-OE enhance the stimulation of erK1/2/MMP2/9 signaling pathway by tumor-derived DNA in HCC cells." (PMID 35860597, 2022). "MMP2 and MMP9, which degrade type IV collagen and gelatin substrates, are highly associated with tumor dissemination, angiogenesis, and invasiveness in various solid tumor types." (PMID 35449123, 2022). "Herein, we detected the expression of MMP-9, CD147, MMP-2, as well as VEGF protein linked to tumor cell migration along with infiltration in MDA-MB-231 cells via Western blot experiment." (PMID 35295962, 2022). "In the invasive tumor group there were two significant correlations: first between MMP-1and MMP-2 expression (rho = 0.306, p = 0.031) and second between TIMP-2 and MMP-9 expression (rho = 0.464, p = 0.001)." (PMID 36551933, 2022). "The active STAT3 signaling pathway is a crucial transcription factor that can directly activate c-Myc, VEGF, MMP2/9, and other molecules, promoting tumor cell proliferation, invasion, metastasis, and angiogenesis." (PMID 35113040, 2022). "Exosomes released by liver and lung tumour cell lines can deliver cir-MMP2 and lnc-MMP2 RNAs to recipient tumour cells, respectively, leading to increased MMP2 expression and an MMP2-mediated invasion of tumour cells." (PMID 35158891, 2022). "After accumulation into tumor tissues, the high-expressed MMP-2 triggered the size shrinkage of nanoparticles and release of DOX." (PMID 35875197, 2022). "It has been reported that MMP-2 plays a vital role in the process of tumor invasion which was regulated by YAP1." (PMID 35961957, 2022). "MMP-2 can further induce angiogenesis in the tumor microenvironment by cleaving the extracellular matrix type IV collagen and coordinating with αvβ3 integrins." (PMID 35458618, 2022). "In contrast to the controls, the protein expressions of CXCR4, CXCL12, CCR7, CCL21, P-ERK1/2, MMP-9, and MMP-2 in SK-Hep1 cells were significantly increased after transfection of tumor-derived DNA, while the increase was reversed by sinobine hydrochloride." (PMID 35860597, 2022). "Then, we analyzed the histoscores of Hsp70, Hif1α, cortactin MMP14, and MMP2 in both tumor and normal tissues and observed significantly higher expression levels of these proteins in OSCC tissues." (PMID 35957827, 2022). "miR-708-5p is a tumor suppressor known to regulate NF-κB subunit p-65, the master regulator of an array of genes and MMP2." (PMID 35615145, 2022). "The cleavage of the PDPPA-1 peptide by highly expressed MMP-2 in the tumor matrix and the further destruction of the disulfide bond by a high concentration of glutathione in tumor cells eventually reduce the size of MB@MSP and reverse the charge." (PMID 35832074, 2022).
tumor (continued). "This SLIPS method obtained a low LOD of 3.7 ng/ml, which has been successfully used for detecting the MMP-2 secreted by tumor cells directly." (PMID 35419350, 2022). "MMP2 is involved in solid tumor vessel formation and shapes the tumor microenvironment to promote tumor progression." (PMID 36230577, 2022). "Previous studies overexpressed matrix metalloproteinases (MMPs) in solid tumor tissues to develop a tumor tissue MMP-2-responsive nano-drug delivery system that co-delivers PD-L1 antibody and photosensitizer indocyanine green (ICG)." (PMID 35664731, 2022). "At the tumor site, the upregulated expression of MMP2/9 degrades these NGs and releases [125I]ITdU, which gets incorporated into the DNA of glioblastoma cells." (PMID 36559325, 2022). "They upregulated expressions of MMP2 and MMP9, which are extracellular membrane-degrading enzymes associated with tumor aggressiveness." (PMID 36230547, 2022). "Several MMPs, including MMP-2 and -9, are mainly produced by stromal cells, and tumor cells are believed to stimulate MMP expression through paracrine signaling." (PMID 35884455, 2022). "Mcl-1, MMP2, and c-Myc mRNA levels were also reduced in the xenograft tumor tissues with TRIM47 knockdown." (PMID 36288633, 2022). "MMP-2 expression was reported to be upregulated in pancreatic cancer and was proven to have positive correlation with the stage and grade of the tumor and with the chances of tumor recurrence." (PMID 36013494, 2022). "MMP2 is likewise involved in the adhesion between tumor cells and mesothelial cells, thereby triggering metastasis." (PMID 36147444, 2022). "More importantly, western blot and tumor immunohistochemical staining assays demonstrated decreased expression of MMP-2, MMP-3, and MMP-9 in the primary 4T1 tumor after D-NPBB94/C-NPBB94 treatment, which further confirmed its excellent therapeutic activity." (PMID 35440570, 2022). "The results of this study showed that these compounds are potentially effective blockers of tumor cell migration and metastasis, by inhibiting MMP-2 and MMP-9 expression and activation through regulation of the MAPK signaling pathway." (PMID 35269801, 2022). "The anti-HCC effect is related to preventing ROS production, inducing DNA oxidation of cancer cells, reducing angiogenesis of tumor cells, blocking stats, and inhibiting MMP2 and MMP9." (PMID 36277879, 2022). "As a member of MMPs, MMP2 is involved in the invasion of a variety of tumor cells by digesting the extracellular matrix barrier." (PMID 36569343, 2022). "The upregulation of GFAP and CX-43 in astrocytes, and the expression of MMP-2 by the tumor cells, promote tumor infiltration." (PMID 35205842, 2022). "The purpose of inhibiting tumor growth was achieved by homotypic targeting of the H460 cell membrane and specific digestion by the MMP2 enzyme, delivering and releasing the TPP-1 peptide that inhibited PD-L1 and PD-1 binding into the tumor microenvironment." (PMID 36005653, 2022). "We sampled the conditional distribution of MMP-2 expression by setting the tumor category as evidence using the wrapper function of cpdist in bnlearn." (PMID 35561164, 2022). "During the same period, Jay’s group showed that eHsp90α from the conditioned medium of tumour cells was required for tumour cell invasion via activation of MMP2 in vitro." (PMID 35883467, 2022). "The protein family of matrix metalloproteinases can degrade extracellular matrix components, whose well-known role is modulating tumor metastases, such as MMP2, MMP9, MMP7, MMP13, and MMP14." (PMID 35690612, 2022). "MMP-2 (main) degrades the extracellular matrix and induces cell migration from the primary tumor to the surrounding environment." (PMID 36741734, 2022). "Remodeling of the ECM allows for the migration of tumor cells, but also endothelial cells, e.g., via the activity of matrix metallopeptidase 2 (MMP2) and matrix metallopeptidase 9 (MMP9)." (PMID 36231134, 2022).